CLIC2 (CLIC family member 2)
Diseases named in the same sentence as CLIC2 in open-access papers (continued):
Sharing a sentence is not in itself a finding about the gene and the disease.
cancer (continued). "Therefore, it is possible that the therapeutic effect on malignant tumors will be further enhanced if not only the effect of CLIC2 is enhanced but also that of CLIC4 is inhibited at the same time." (PMID 36230813, 2022). "CLIC2 or related endogenous mechanisms may be used to create new therapeutic strategies against the invasion and metastasis of malignant tumors." (PMID 36230813, 2022). "CLIC2, in particular, was predominantly expressed in non-cancer tissues surrounding cancer masses where may be involved in the formation or maintenance of tight junctions which allows the intravasation of cancer cells to form metastasis." (PMID 34357102, 2021). "Increasing expression of CLIC2 in cancer or surrounding cells could prevent the invasion of cancer cells, and thus local progression and distant metastasis." (PMID 32116799, 2020). "Understanding of the involvement of CLIC2 in cancer cells or tumorigenesis is limited." (PMID 32116799, 2020). "Ueno and colleagues also indicated that CLIC2 may be involved in the maintenance of tight junctions, and that cancer vasculature endothelial lacks CLIC2, allowing the hematogenous metastasis of cancer cells." (PMID 32915772, 2020). "However, CLIC2 mRNA expression in small tumor or early-stage cancer tissue was significantly higher than in larger tumor or advanced-stage cancer tissue, respectively." (PMID 32915772, 2020). "Therefore, we examined CLIC2 expression in human cancer tissues." (PMID 36230813, 2022). "However, if CLIC2 expression can be increased in malignant tumor tissues and/or surrounding tissues, there is a strong possibility that cell–cell junctions, particularly those between vascular endothelial cells, will be strengthened and hematogenous metastasis will be suppressed." (PMID 36230813, 2022). "This further indicates that CLIC2 could be a new target molecule in cancer therapy." (PMID 36230813, 2022). "However, while there is a lack of extensive studies on CLIC2 in animal models, it is differentially associated with patient survival in various cancers as shown in K-M plots." (PMID 32116799, 2020). "However, few studies have reported that CLIC2 had a physiological function in cancer or immunity." (PMID 32915772, 2020). "We found that the expression of CLIC4 was increased in cancer tissues; however, the mRNA expression of CLIC2 and CLIC6 was lower in HCC tissues than in non-cancer tissues." (PMID 34766585, 2021). "In addition, the study reported that CLIC2 predominantly expressed in endothelial cells lining blood vessels, but not lymphatic vessels, in noncancerous tissues surrounding cancer masses, in which blood vessels might be in a state of loss-of-function of CLIC2." (PMID 32915772, 2020). "CLIC4 is a probable detrimental factor for cancer prognosis, and this may be attributable to its stimulating effect on MMP activities, opposite to CLIC2." (PMID 36230813, 2022). "The expression of CLIC2 and tight junction proteins is upregulated in non-cancer, compared with cancer cells, and CLIC2 regulates the formation of tight junction proteins such as claudin 1, claudin 5, zonula occludens-1, and occludin." (PMID 35205604, 2022). "With respect to MMP14 activity, CLIC2 and CLIC4 have opposite effects, and CLIC2 may act in an inhibitory and CLIC4 in a promotive manner with respect to the metastasis and invasion of malignant tumors." (PMID 36230813, 2022). "In contrast, blood vessel endothelial cells in cancer tissues and lymphatic endothelial cells that lacked CLIC2 expression did not express tight junction proteins." (PMID 36230813, 2022). "CLIC2 is not reported as a cancer gene in the network of cancer genes’ (NCG 6.0) collection of sources of known cancer genes and 273 cancer mutation screenings." (PMID 32116799, 2020). "However, most blood vessel endothelial cells in cancer tissues and lymphatic endothelial cells in normal and cancer tissues did not express CLIC2." (PMID 36230813, 2022).
cancer (continued). "Immunohistochemical analysis revealed that cancer cells did not express CLIC2." (PMID 36230813, 2022). "However, recently it was shown that CLIC2 is highly expressed in non-cancerous cells surrounding cancer masses." (PMID 32116799, 2020). "Some of the intracellular chloride channels from CLIC and other families are envisioned as proteins that “may contribute to a cancer phenotype”, however, no significant role for CLIC2 has been previously reported." (PMID 26191006, 2015).
tumor (10 papers, 2020 to 2025). "The second possibility is that tumor cells express CLIC2 that binds to MMP14 intracellularly while inhibiting the enzyme activity." (PMID 36230813, 2022). "The mechanism by which CLIC2 improves the tumor prognosis involves maintaining tight junctions and cadherin-mediated adherence junctions of blood vessels, which inhibit hematogenous distant metastasis." (PMID 36230813, 2022). "Most of the TMEM119+ FIBs appeared to be positioned peripherally and juxtaposed to KRT14+ tumor nests, to a greater extent than those observed for CLIC2+ and CEMIP+ FIBs or sparse ASPN+ FIBs." (PMID 35687691, 2022). "CLIC2 is expressed at higher levels in benign tumors than in malignant ones, most likely preventing tumor cell invasion into surrounding tissues." (PMID 36230813, 2022). "If CLIC2 is expressed on tumor cells themselves, what changes in metastasis and invasion of the tumor cells occur?" (PMID 36230813, 2022). "The results obtained using the two different tumor models show that CLIC2 expression inhibits the invasion and metastasis of malignant cells." (PMID 36230813, 2022). "Furthermore, in the same samples, MMP2 activation was suppressed in grade I tumor masses with abundant CLIC2 protein expression." (PMID 36230813, 2022). "Because there have been few studies on CLIC2 in relation to malignant tumor progression, the significance and roles of CLIC2 expression in tumor cells were unknown." (PMID 36230813, 2022). "In situ, CLIC2+ FIBs are located sparsely surrounding KRT14+ tumor cell nests." (PMID 35687691, 2022). "The third possibility is that tumor cells secrete CLIC2 that inhibits MMP activities in the extracellular milieu, resulting in the maintenance of intercellular adhesion and extracellular matrix leading to the prevention of invasion and metastasis of tumor cells." (PMID 36230813, 2022). "The factors that regulate CLIC2 expression levels in normal and tumor tissues must be identified." (PMID 36230813, 2022). "As a result, CLIC2 may contribute to the development/maintenance of junctions between blood vessel endothelial cells and the inhibition of invasion and metastasis of tumor cells." (PMID 36230813, 2022). "This indicates that the expression of CLIC2 in tumor cells as well as in endothelial cells may prevent the increase in vascular permeability." (PMID 36230813, 2022). "CLIC2 inhibits tumor cell invasion and metastasis by suppressing MMP14 activity." (PMID 36230813, 2022). "In addition, such effects were inversely reported in our recent report on microglia, suggesting a distinct role for CLIC2 in immune and tumor cells." (PMID 36672037, 2022). "CLIC2 is identified as a novel gene related to immune checkpoint proteins based on TCGA gene expression data, while another study suggests that it inhibits the hematogenous spread of tumor cells." (PMID 33428606, 2021).
benign tumors (2 papers, 2022 to 2024). "However, the observation that recombinant CLIC2 can inhibit malignant cell invasion by suppressing MMP activity helps to explain why normal tissues and benign tumors do not undergo metastatic invasion." (PMID 36230813, 2022).
CLIC2 also shares sentences with these, for which no sentence is quoted: congestive heart failure (2 papers); epilepsy (2); Hypertension (2); lung carcinoma (2); atrial fibrillation (1); autism (1); bladder urothelial carcinoma (1); cardiac hypertrophy (1); cholangiocarcinoma (1); colorectal cancer (1); dilated cardiomyopathy (1); glaucoma (1); head and neck squamous cell carcinoma (1); infection (1); kidney carcinoma (1); kidney chromophobe (1); learning disabilities (1); lung adenocarcinoma (1); prostate adenocarcinoma (1); rectum adenocarcinoma (1); thyroid carcinoma (1); uterine corpus endometrial carcinoma (1).